GARS1 (glycyl-tRNA synthetase 1)
Description:
Catalyzes the ATP-dependent ligation of glycine to the 3'-end of its cognate tRNA, via the formation of an aminoacyl-adenylate intermediate (Gly-AMP). Also produces diadenosine tetraphosphate (Ap4A), a universal pleiotropic signaling molecule needed for cell regulation pathways, by direct condensation of 2 ATPs. Thereby, may play a special role in Ap4A homeostasis.
Synonyms: GlyRS; GARS; DSMAV; SMAD1; CMT2D; HMN5; HMN5A; HMND5; SMAJI
Tractability: Small molecule: a structure with a bound ligand is known; it has a high-quality binding pocket. Antibody: UniProt places it where antibodies can reach, with medium confidence; its Gene Ontology location is reachable by antibodies, with medium confidence. PROTAC: ubiquitination databases record sites on it; a small molecule that binds it is known.
Target class: Enzyme; Hydrolase
Safety:
Unwanted effects reported when the protein is acted on. In parentheses: how it was acted on, where the effect was seen, and who reports it.
asthma (source: ClinPGx)
Gene: Protein-coding gene on chromosome 7 (30,580,533 to 30,634,033, forward strand). Ensembl gene ENSG00000106105.
Subcellular location: Cytoplasm; Cell projection, axon; Secreted; Secreted, extracellular exosome; Mitochondrion (Isoform 1); Cytoplasm (Isoform 2)
Subcellular location (Human Protein Atlas): Cytosol
Pathways (Reactome):
Metabolism of proteins: Cytosolic tRNA aminoacylation; Mitochondrial tRNA aminoacylation
Gene Ontology:
Molecular function: ATP:ATP adenylyltransferase activity; bis(5'-nucleosyl)-tetraphosphatase (asymmetrical) activity; glycine-tRNA ligase activity; identical protein binding; protein binding; protein dimerization activity; aminoacyl-tRNA ligase activity; ATP binding; nucleotide binding
Biological process: diadenosine tetraphosphate biosynthetic process; tRNA aminoacylation for protein translation; mitochondrial glycyl-tRNA aminoacylation; glycyl-tRNA aminoacylation
Cellular component: axon; cytoplasm; cytosol; mitochondrion; extracellular exosome; extracellular region; mitochondrial matrix; secretory granule
Genetic constraint (gnomAD): Loss-of-function variants: 34 observed, 69.85 expected, observed/expected ratio (o/e) 0.49, 90% interval 0.37 to 0.65. The upper end of that interval is the gene's LOEUF score, 0.65, which puts it in group 2 of 6, group 1 being the genes least tolerant of losing a copy. Missense variants: 725 observed, 847.03 expected, observed/expected ratio (o/e) 0.86, 90% interval 0.8 to 0.91. Synonymous variants: 321 observed, 306 expected, observed/expected ratio (o/e) 1.05, 90% interval 0.96 to 1.15.
Gene-disease validity (ClinGen):
ClinGen rates the evidence that GARS1 causes each of these diseases.
Charcot-Marie-Tooth disease type 2D (autosomal dominant): Definitive.
Homologues: Orthologues: chimpanzee GARS1 (99% identical), macaque GARS1 (98% identical), pig GARS1 (95% identical), dog GARS1 (94% identical), mouse Gars1 (91% identical), rat Gars1 (91% identical), guinea pig GARS1 (90% identical), rabbit GARS1 (88% identical), tropical clawed frog gars1 (83% identical), zebrafish gars1 (81% identical), Drosophila melanogaster GlyRS (57% identical), Caenorhabditis elegans gars-1 (54% identical). Paralogues in human: POLG2 (14% identical).
Diseases named in the same sentence as GARS1 in open-access papers:
GARS1 is named in the same sentence as 59 diseases in open-access papers, as found by Europe PMC text mining. Sharing a sentence is not in itself a finding about the gene and the disease. The quoted sentences say what the papers report.
neuropathy (13 papers, 2015 to 2025). A disorder affecting the nervous system that manifests with pain, tingling, numbness, and/or muscle weakness. "Despite the different disease classifications, there is substantial phenotypic overlap between the GARS1-associated neuropathies." (PMID 37274211, 2023). "Neuropathy-causing GARS1 mutations differentially impact the enzymatic activity, with some fully ablating it, whilst others having little effect." (PMID 32848623, 2020). "Together, these findings indicate that neuropathy-causing GARS1 mutations impair axonal transport of neurotrophin-containing signaling endosomes in motor neurons in vivo and that human mutant GlyRS injected into muscle can induce this phenotype in wild-type mice." (PMID 36928301, 2023). "While developmental demand may contribute to early synaptic disruption, GARS1-associated neuropathy is progressive and denervation continues in CMT2D mice up to 3 months and beyond." (PMID 32703932, 2020). "Impaired protein synthesis is thus a major component of GARS1 neuropathy, as well as other diseases affecting peripheral nerves; however, the driver of differential vulnerability in neuropathy across motor and sensory neuron subtypes remains undetermined." (PMID 36928301, 2023). "Neuromuscular degeneration is replicated in a Drosophila melanogaster model for GARS1 neuropathy and is dependent on toxic accumulation of mutant GlyRS at the NMJ19." (PMID 32703932, 2020). "Sensory dysfunction of GARS1-neuropathy patients and mouse models of CMT2D is chronically understudied." (PMID 32848623, 2020). "In contrast, despite reducing Gars1 expression by 50%, heterozygous Gars1 knockout in mice (Gars1XM256/+) does not trigger a disease phenotype, demonstrating that the neuropathy is not caused by haploinsufficiency." (PMID 37274211, 2023). "The pathological impact of mutant GlyRS on the sensory nervous system is therefore relatively under-studied and requires further attention if we are to elucidate the cause of its varied involvement in GARS1-linked neuropathy." (PMID 32848623, 2020). "Neuropathy-associated GARS1 mutations have been shown to impair GlyRS localization in neuron-like cell lines, which could cause build-up in the soma, although, once again, if this were the cause of increased GlyRS levels then it would probably not be so selectively upregulated." (PMID 32848623, 2020).
Charcot-Marie-Tooth disease (11 papers, 2014 to 2025). An inherited degenerative disorder involving the peripheral nerves. "Gain-of-function mutations in the housekeeping gene GARS1, which lead to the expression of toxic versions of glycyl-tRNA synthetase (GlyRS), cause the selective motor and sensory pathology characterizing Charcot-Marie-Tooth disease (CMT)." (PMID 36928301, 2023). "For example, our model correctly classified all 14 pathogenic variants for Charcot-Marie-Tooth disease, despite their being spread in different genes (LMNA, MFN2 and GARS1)." (PMID 41155097, 2025). "The most common condition, the Charcot-Marie-Tooth disease (CMT), is associated with dominant, monoallelic mutations in six aaRSs genes (e.g.,YARS1, MARS1, KARS1, WARS1, AARS1, GARS1, and HARS1)." (PMID 37495112, 2023). "Thus far, autosomal dominant mutations in AARS1, GARS1, HARS1, MARS1, WARS1, SARS1 and YARS1 have been linked to peripheral neuropathies, predominantly Charcot-Marie-Tooth (CMT) disease." (PMID 37274211, 2023).
autism spectrum disorder (4 papers, 2017 to 2023). A spectrum of developmental disorders that includes autism, and Asperger syndrome. "Besides adolescent‐onset or infant‐onset neuromuscular disorders, GARS1 mutations had been reported to be associated with other diseases such as mitochondrial disease, autism spectrum disorder, and a multisystem developmental syndrome that includes severe growth retardation." (PMID 34898052, 2022).
breast carcinoma (3 papers, 2018 to 2024). "Previous studies have demonstrated that GARS1 promotes the cell cycle, migration, and invasion of breast cancer cells by regulating the AKT/mTOR signaling pathway." (PMID 37404826, 2023). "GARS1 overexpression has been associated with poorer prognosis in lung adenocarcinoma patients, while inhibition of GARS1 impedes the growth and colony formation of breast cancer cells, and depletion of GARS1 hinders cell proliferation and cell cycle progression in hepatocellular carcinoma (HCC)." (PMID 37404826, 2023).
prostate carcinoma (3 papers, 2022 to 2024). A carcinoma that arises from epithelial cells of the prostate gland. "GARS1 and KARS1 display androgen-dependent transcriptional initiation in several hormone-responsive cells, such as prostate cancer cells 19; thus, transcription of GARS1 and KARS1 is initiated in cancers with increases in AREs." (PMID 35501376, 2022). "The pathogenetic role of GARS1 in oncology has recently been confirmed by a publication reporting that the silencing of GARS1 expression is effective in counteracting the progression of prostate cancer." (PMID 38235113, 2023).
axonal neuropathy (2 papers, 2022 to 2023). Any nerve disorder affecting the axon of a nerve. "Both Charcot‐Marie‐Tooth disease type 2D (CMT2D) and distal spinal muscular atrophy type V (dSMA‐V) are GARS1 disease phenotypes involving axonal peripheral neuropathy." (PMID 34898052, 2022). "DSMAV and CMT2D can be caused by the same GARS1 mutations, suggesting that these conditions represent a spectrum of GARS1 associated axonal neuropathy, rather than distinct diseases." (PMID 37274211, 2023).
hepatocellular carcinoma (2 papers, 2023). A malignant tumor that arises from hepatocytes. "GARS1 mRNA overexpression, found at the tissue level, has recently been linked to poor prognosis for hepatocellular carcinoma and was selected as a urinary protein marker for the diagnosis of urothelial carcinoma." (PMID 38235113, 2023).
lung adenocarcinoma (2 papers, 2023). A carcinoma that arises from the lung and is characterized by the presence of malignant glandular epithelial cells. "Multi-omics analysis, evaluating genetic alteration and prognostic value of transcriptional dysregulation, shows GARS1 to have the highest association with cancer out of all the ARSs, especially for lung adenocarcinoma." (PMID 38235113, 2023). "Furthermore, higher levels of GARS1 mRNA are associated with significantly poorer survival rates in different cancer types, among which is lung adenocarcinoma, thus confirming the pathogenic role of this protein in cancer development." (PMID 38235113, 2023).
spinal muscular atrophy (2 papers, 2015 to 2024). A motor neuron disease that affect the muscles, and characterized by muscle weakness and atrophy resulting from progressive degeneration and irreversible loss of the anterior horn cells in the spinal cord (i.e., lower motor neurons) and the brain stem nuclei. "Two pathogenic variants resulting in a missense modifying amino acid at codon 336 in the catalytic domain of GARS1, were found in two unrelated patients - one a female with infantile spinal muscular atrophy; and the second, a male with Charcot–Marie–Tooth disease type 2D." (PMID 38317844, 2024).
autoimmune disease (1 paper, 2023). A disorder resulting from loss of function or tissue destruction of an organ or multiple organs, arising from humoral or cellular immune responses of the individual to their own tissue constituents. "Previous studies primarily focused on GARS1 have centered around human autoimmune diseases and neuronal disorders." (PMID 37404826, 2023).
bladder cancer (1 paper, 2023). "Due to the favourable prognostic significance and immune predictive value of GARS1 in bladder cancer, we conducted further investigations into its biological functions in bladder cancer cells." (PMID 37404826, 2023). "To further validate the involvement of GARS1 in tumor progression, we specifically chose bladder cancer cells for our experimental investigation." (PMID 37404826, 2023). "Initially, we validated the high expression of GARS1 in multiple bladder cancer cell lines using qRT-PCR and Western Blot assay." (PMID 37404826, 2023). "The findings indicated a significant upregulation of GARS1 in bladder cancer cells, and its elevated expression notably stimulated the proliferation and migration of these cells." (PMID 37404826, 2023). "Our experimental findings strongly suggest that GARS1 promotes the proliferation and migration of bladder cancer cells." (PMID 37404826, 2023). "In conclusion, GARS1 promotes the proliferation and migration of bladder cancer cells." (PMID 37404826, 2023). "Finally, we conducted cellular experiments to validate the biological significance of GARS1 in bladder cancer cells." (PMID 37404826, 2023). "Furthermore, experimental evidence substantiates that GARS1 enhances the proliferation and migration of bladder cancer cells." (PMID 37404826, 2023).
distal hereditary motor neuronopathy (1 paper, 2021). "Mutant GlyRS encoded by GARS1 causes autosomal dominant CMT2D and distal hereditary motor neuronopathy." (PMID 34483837, 2021).
non-small cell lung carcinoma (1 paper, 2023). A group of at least three distinct histological types of lung cancer, including non-small cell squamous cell carcinoma, adenocarcinoma, and large cell carcinoma. "Conclusion and implications: The overall results indicate that Fraisinib is a powerful inhibitor of non-small-cell lung cancer growth by exerting its action on the enzyme GARS1 while displaying marginal toxicity in animal models." (PMID 38235113, 2023).
retinoblastoma (1 paper, 2023). A malignant tumor that originates in the nuclear layer of the retina. "In Retinoblastoma, GARS1 exhibits a noteworthy positive correlation with biological functions related to Differentiation, Angiogenesis, Inflammation, while showing a significant negative correlation with CellCycle, DNA damage, DNA repair." (PMID 37404826, 2023). "In retinoblastoma (RB), GARS1 exhibited a significant positive correlation with biological functions like differentiation, angiogenesis, and inflammation, while displaying a significant negative correlation with biological functions such as cell cycle, DNA damage, and DNA repair." (PMID 37404826, 2023).
uveal melanoma (1 paper, 2023). A melanoma derived from melanocytes of the uveal tract. "Conversely, in Uveal Melanoma, GARS1 demonstrates predominantly negative correlations with various biological functions." (PMID 37404826, 2023). "Furthermore, predominantly negative correlations were observed between GARS1 and diverse biological functions in uveal melanoma (UM)." (PMID 37404826, 2023).
cancer (15 papers, 2020 to 2025). A tumor composed of atypical neoplastic, often pleomorphic cells that invade other tissues. "Based on these findings, we observed that GARS1 was associated with prognosis in the majority of tumors, indicating its potential as a prognostic biomarker for a wide range of cancers." (PMID 37404826, 2023). "The results revealed significant associations between GARS1 and various cancer-related functions, displaying distinctive patterns among different tumor types." (PMID 37404826, 2023). "Although the enzymatic activity of GARS1 is principally involved in the first essential step of protein synthesis, other functions associated with cancer evolution and cellular homeostasis have been described in the last decade." (PMID 38235113, 2023). "The role of GARS1 in cancer progression was recently linked to the additional functionality of this protein in regulating neddylation, a post-translational modification involved in cell cycle regulation and proliferation." (PMID 38235113, 2023). "GARS1 emerges prominently in all analyses as the aminoacyl-tRNA synthetase (aaRS) most strongly associated with cancer." (PMID 38235113, 2023). "Compared with KARS1, GARS1 predominantly features gene amplification in cancers, whereas KARS1 features more deletions and mutations than amplifications." (PMID 33266490, 2020). "Notably, CD274 (PD-1) exhibits a significant positive correlation with GARS1 expression in 15 cancer types, emphasizing the strong association between GARS1 and tumor immunotherapy." (PMID 37404826, 2023). "GARS1 stands out in all analyses as the most cancer-associated aaRS." (PMID 33266490, 2020). "Moreover, these variations manifest in diverse cancer types, suggesting that GARS1 mutations could contribute to carcinogenesis." (PMID 37404826, 2023). "In the majority of tumors, a significant negative correlation was observed between GARS1 expression and immune score as well as estimate score, implying the predominant expression of GARS1 in cancer cells." (PMID 37404826, 2023). "Collectively, these findings highlight the intricate relationship between GARS1 and immune cell activation in the context of anti-cancer immune responses, thereby providing valuable insights for further investigations into GARS1-related tumor immunotherapy." (PMID 37404826, 2023). "In contrast to other ARSs, GARS1 predominantly exhibits gene amplification in various cancer types, while other proteins tend to feature more deletions and mutations rather than amplifications." (PMID 38235113, 2023). "In cancer cell lines, we noted elevated expression of GARS1 in cell lines originating from lymphatic and hematopoietic system tumors." (PMID 37404826, 2023). "In conclusion, these findings provide evidence supporting the potential involvement of GARS1 in the immune response in cancer." (PMID 37404826, 2023). "In general, GARS1 expression was significantly upregulated across multiple cancer types, and it demonstrated prognostic value in various cancers." (PMID 37404826, 2023). "In this study, we comprehensively analyzed GARS1 expression at the mRNA and protein levels, examined genetic alterations, and assessed its prognostic implications in pan-cancer, with a specific emphasis on the immune landscape." (PMID 37404826, 2023). "In our study, GARS1 exhibited upregulation in the majority of cancer tissues compared to adjacent normal tissues, and its high expression was correlated with a poor prognosis in most tumors." (PMID 37404826, 2023). "In conclusion, GARS1 is extensively upregulated in cancer and possesses the capacity to predict prognosis across diverse types of cancer." (PMID 37404826, 2023). "In this study, we conducted a comprehensive analysis of GARS1 expression and survival disparities across various cancers, utilizing transcriptome sequencing and single-cell sequencing data." (PMID 37404826, 2023).